IL1B (interleukin 1 beta)
Diseases named in the same sentence as IL1B in open-access papers (continued):
Sharing a sentence is not in itself a finding about the gene and the disease.
synovitis (continued). "Previous works of literature reported that TNF-α and IL-1β are closely related to cartilage destruction and the occurrence of synovitis." (PMID 37187885, 2023). "Intra-articular lavage and interleukin 1 beta (IL-1β)-induced synovitis are two transient experimental models used to mimic clinical synovitis and study early joint disease in a controlled manner without the requirement for euthanasia." (PMID 33980227, 2021). "Synovitis models are well established in horses, with lipopolysaccharide (LPS) and IL-1β being the most frequently used, and IL-1β-induced synovitis considered a more appropriate model for early OA due to the known contribution of IL-1β to OA pathogenesis." (PMID 33980227, 2021). "The objectives of this study were to evaluate clinical signs; synovial membrane and synovial fluid inflammation; and synovial fluid lubricants and biophysical properties in response to carpal IL-1β synovitis and tarsal intra-articular lavage." (PMID 33980227, 2021). "An equine model of amphotericin B-induced synovitis showed a delayed but sustained elevation of IL-1β and TNF-α over the 9-week study period." (PMID 33980227, 2021). "Synovitis, involving the infiltration of mononuclear cells into the synovial membrane and the production of proinflammatory mediators, including IL-1β, TNF-α and chemokines, is common in early stage and late stage disease." (PMID 33669093, 2021). "With regard to comparison of the low-grade and high-grade groups with different grades of synovitis, expression levels of IL1B, CXCL8, TNF, and PTGS2 were significantly higher in the high-grade group than in the low-grade group." (PMID 33507995, 2021). "Synovial fluid IL-1β protein concentrations have also been shown to increase in horses 8 h after LPS-induced synovitis and in horses with naturally occurring OA." (PMID 33980227, 2021). "Contrary to previous in vitro reports, synovial fluid lubricin increases in response to IL-1β-induced synovitis and joint lavage in vivo." (PMID 33980227, 2021). "Repeated arthrocentesis is necessary for studies designed to measure changes in synovial fluid constituents over time and has been employed in nearly all studies evaluating IL-1β or LPS-induced synovitis in horse." (PMID 33980227, 2021). "Synovial fluid clinicopathological and biochemical parameters were used to both validate the IL-1β synovitis model and to compare inflammatory changes between the IL-1β synovitis and lavage models." (PMID 33980227, 2021). "Synovitis can be sustained by cytokines such as IL-1β and TNF-α, which can further promote the production of MMPs and other proteinases." (PMID 33053109, 2020). "The synovitis scores as well as the levels of IL-1β and TNF-α suggested that PEMF reduced the severity of synovitis in vivo." (PMID 32596310, 2020). "Our findings indicated that CS/HA/pIL-1Ra nanoparticles efficiently transfected synoviocytes and attenuated synovitis induced by IL-1β, which will provide a potential strategy for OA synovitis." (PMID 30276528, 2018). "In patients with grade 3 cases of synovitis, the levels of TNFα, IL1β, IL6, and MMP1 were significantly increased compared with those in cases of grade 2 synovitis (p < 0.05)." (PMID 28425031, 2017). "In general, the joint organization of IL1β induced synovitis and cartilage matrix components degradation." (PMID 27869674, 2016). "In this regard, pro-inflammatory cytokines such as IL-1β play a role in driving synovitis during OA and influencing the production of cytokines and MMPs." (PMID 20799933, 2010). "It is noteworthy that the combined effect of mitophagy and pyroptosis leads to inflammatory changes in synovial fibroblasts (FLS), and through the continuous secretion of inflammatory factors such as IL-1β and IL-18 ultimately promotes the progression of synovitis." (PMID 40728955, 2025).
synovitis (continued). "In the context of OA specifically, cartilage cell-derived exosomes can affect macrophage behavior, instigating synovitis and exacerbating OA through intricate pathways involving the microRNA (miR)-449a-5p and autophagy cascades, thereby modulating the interleukin 1 beta (IL-1β) release." (PMID 38059912, 2024). "Additionally, we identified the essential omega-3 fatty acid DPA as a potential therapeutic agent for synovitis, demonstrating efficacy in blocking the transcription and expression of IL-1β and IL-6 with minimal side effects." (PMID 38734632, 2024). "Synovitis, trauma or injury can lead to activation of the mechanoreceptors, which in turn can stimulate an inflammatory response with the release of pro-inflammatory cytokines and degradative enzymes (IL-1B and TNF-alpha and MMPs)." (PMID 39765549, 2024). "It is well-known that IL-1β acts as a key mediator in activating the NF-κB signaling pathway, which subsequently stimulates the proliferation of synovial fibroblasts and leads to synovitis." (PMID 38545550, 2024). "Moreover, our results suggest that IL-1β and IL-6 are pivotal inflammatory factors in meniscal tears-induced synovitis." (PMID 38734632, 2024). "Additionally, our results indicated that the expression of IL-1β and IL-6 varied among different synovial tissue sections within the same type of synovitis, and its expression in the anterior medial region was significantly higher." (PMID 38734632, 2024). "However, activated synoviocytes in inflammatory synovitis produce and release a large number of pro-inflammatory factors when synovitis occurs, such as IL-1β, IL-6, MMPs and TNF-α, which mediate cartilage destruction and TMJ inflammation through various ways." (PMID 38053836, 2023). "This is the first report to demonstrate an increase in synovial fluid lubricin following either IL-1β-induced synovitis or intra-articular lavage, contrary to our hypotheses." (PMID 33980227, 2021). "Persistent synovitis is one of the characteristics of RA, which is mainly caused by the continuous migration of immune cells into the joints and the continuous production of various proinflammatory cytokines, of which chemokines, TNF-α, and IL-1β play a crucial role in synovitis." (PMID 34691317, 2021). "The absent response in IL-1β concentration and the brief TNF-α increase observed in IL-1β-induced synovitis joints differ from previous findings in the amphotericin B-induced synovitis model, which showed a sustained increase in concentration of these cytokines in synovial fluid for 9 weeks." (PMID 33980227, 2021). "Here, we compare the well-established carpal IL-1β-induced synovitis model to a tarsal intra-articular lavage model, focusing on serial changes in synovial fluid inflammatory cytokines/chemokines and the synovial fluid lubricating molecules lubricin/proteoglycan 4 and hyaluronic acid." (PMID 33980227, 2021). "Taken together with the in vitro results, it was speculated that PTX alleviated synovitis might be related to the inhibition of cell migration and the expression of IL-1β, IL-6, and IL-8." (PMID 34566640, 2021). "Therefore, it is possible that feline synovial fibroblasts stimulated by IL-1β are a model of synovitis in OA." (PMID 28054591, 2017). "Furthermore, the experiments in vitro were carried out to examine the subsequent IL-1Ra gene overexpression and its anti-inflammatory effect in inflammation induced by IL-1β in synoviocytes, which have offered insights to explore potential therapeutic strategies for OA synovitis." (PMID 30276528, 2018). "Inflammatory markers such as IL‐1β, IL‐6, TNF‐α and MMP1 increased with synovitis or severe chondral damage." (PMID 40989937, 2025). "Proinflammatory cytokines, such as IL-6, IL-1β, and TNF-α, contribute to the destruction of cartilage and synovitis." (PMID 38913985, 2024). "In a synovitis cell model constructed using IL-1β, HMGB1, and LPS, intracellular IL-37 was responsively upregulated (more pronounced with stimulation of IL-1β)." (PMID 38053836, 2023).
synovitis (continued). "TP-VP NPs effectively down-regulated IL-1β, IL-6 and TNF-α levels to inhibit the erosion of synovitis and bone tissue, and alleviate the swelling and deformation of CIA mice’s feet." (PMID 35999774, 2022). "In animal experiments, the topical application of SP-NEs gel paste can effectively reduce synovitis of KOA rats and downregulate the gene and protein expressions of IL-1β, IL-18, and TRPA1." (PMID 34876884, 2021). "Expression levels of IL1B, IL6, CXCL8, TNF, PTGS2, and PTGER4 showed significant positive correlations with synovitis score." (PMID 33507995, 2021). "Expression levels of IL1B, IL6, CXCL8, TNF, PTGS2, and PTGER4 showed significant positive correlation with synovitis score." (PMID 33507995, 2021). "Pro-inflammatory cytokines, such as interleukin 1β (IL-1β) and tumor necrosis factor α (TNF-α), play a crucial role in the development of synovitis and progressive joint destruction." (PMID 33117381, 2020). "Synovitis generates inflammatory mediators (TNF-α and IL-1β) that are released into the synovial cavity." (PMID 32566090, 2020). "In this study, we established a model for IL-1β-induced synovitis and investigated the role of NF-κB and MAPK signaling in synovitis." (PMID 33117381, 2020). "This protection is only achieved when ASCs are applied in early CiOA, which is characterized by synovitis and high S100A8/A9 and IL-1β levels, suggesting that inflammation is a prerequisite for the protective effect of ASCs." (PMID 31191517, 2019). "A previous report has indicated that FA had the ability to decrease the levels of hydrogen peroxide-induced IL-1β, TNF-α, MMP-1, and MMP-13, thereby reducing bone destruction, synovitis, and the erosion of cartilage in antigen-induced arthritis." (PMID 24883069, 2014). "A distinct TNF expression was observed in the lining layer as well as in sublining areas in synovitis, whereas HMGB1 and IL-1β expressions were most often restricted to the sublining areas." (PMID 17397533, 2007). "Immunohistochemical studies have found that, particularly in early OA, this synovitis has a mononuclear cell infiltrate, with considerable production of proinflammatory cytokines like TNF-α and IL-1β and destructive enzymes like MMP-1 and MMP-3." (PMID 17177994, 2006). "Our synovial findings align more closely with Görtz’s TNF-driven synovitis model, suggesting that JNK activation in hip OA synovium may require specific inflammatory triggers beyond the basal TNF-α/IL-1β milieu." (PMID 41463004, 2025). "In the present study, the level of MMP1 was significantly higher in the synovial membrane of patients with diffuse synovitis, than in those with focal synovitis, suggesting that severe synovitis can progress to catabolic chondral degeneration via MMP1, which is mediated by TNFα and IL1β." (PMID 28425031, 2017). "The similarities between IL-1β and HMGB1 expressions in synovitis are noteworthy." (PMID 17397533, 2007). "Taken together, the effective inhibition ability of IL-1β and IL-6, and the absence of obvious side effects further support DPA as a promising agent for synovitis treatment." (PMID 38734632, 2024). "The association between synovitis and further OA progression has also been demonstrated.[12a] Therefore, we simulated a “synovitis” model in miniJoint by challenging only SFT with IL‐1β (10 ng/ml), without directly exposing other tissues to exogenous IL‐1β." (PMID 35436042, 2022). "Although bevacizumab did not decrease IL1B expression significantly, we suggest that the decrease in MMP13 and ADAMTS5 expression levels contributed to the absence of synovitis." (PMID 25230745, 2014).
systemic inflammatory response syndrome (68 papers, 2008 to 2026). SIRS is a serious condition related to systemic inflammation, organ dysfunction, and organ failure. "While interleukin (IL)-1β is a potent pro-inflammatory cytokine involved in host defense, high levels can cause life-threatening sterile inflammation including systemic inflammatory response syndrome." (PMID 29922281, 2018). "Elevated systemic levels of IL-1β can cause fever, shock, systemic inflammatory response syndrome (SIRS) and can lead to life-threatening multi-organ damage." (PMID 28725182, 2017). "The cytokines, such as TNF-α and IL-1β, are closely relatedto the occurrence and development of systemic inflammatory response syndrome." (PMID 33503219, 2021). "The NLR Family Pyrin Domain-Containing 3 (NLRP3) inflammasome/caspase-1/IL-1β pathway may be involved to some extent in the occurrence of systemic inflammatory response syndrome (SIRS)." (PMID 40041174, 2025). "Although multiple studies have shown that caspase-8 can directly cleave pro-IL-1β into mature IL-1β in circumstances such as TNF-α-induced systemic inflammatory response syndrome (SIRS), mature IL-1β fragments were undetectable in caspase-1-deficient macrophages upon nigericin treatment." (PMID 41208996, 2025). "Furthermore, patients with systemic inflammatory response syndrome possess higher plasma levels of IL-8, IL-1β, and TNF-α, which induce NET formation in PMN from healthy individuals." (PMID 39749330, 2024). "As expected, severely affected fish (the SL group) demonstrated the pathophysiology of systemic inflammatory response syndrome with activation of circulating granulocytes, releasing pro-inflammatory cytokines il1b and il8, and concomitant secondary organ damage." (PMID 36230384, 2022). "Both TNF-α and IL-1β are major players in the hierarchy of proinflammatory mediator cascades, while nitric oxide (NO) and oxygen free radicals are secondary effectors of cardiac depression in systemic inflammatory response syndromes." (PMID 35707040, 2022). "Similarly, it is shown that lower IL-6 and IL-1β were conducive to protect against lethality in sepsis syndrome via the JNK signaling pathway and the transcription factor AP-1." (PMID 32802115, 2020). "Central to this process is the cytokine storm, driven by uncontrolled release of TNF-α, IL-1β, and IL-6, which exacerbates systemic inflammatory response syndrome (SIRS) and tissue injury." (PMID 41262247, 2025). "All donkeys developed typical features of a systemic inflammatory response syndrome (SIRS) such as tachycardia, fever, and an increase in plasma TNFα and IL-1β concentrations from 30 min PLI (data previously published)." (PMID 40805061, 2025). "The systemic inflammatory response syndrome (SIRS), hallmark sign of sepsis, is characterized by a systemic inflammatory response with massive release of proinflammatory cytokines such as TNF-α, IL-1β, chemokines, nitric oxide, leukotrienes, reactive oxygen species." (PMID 22312472, 2011). "In the same way, IL-6 induces hepatic synthesis of acute phase proteins, and IL-1β and TNF-α participate in systemic inflammatory response syndrome and multiple organ failure." (PMID 40868835, 2025). "In the early stages of sepsis, a subset of activated macrophages, characterized by their expression of proinflammatory markers such as TNF-α, IL-1β, and IL-6, plays a pivotal role in activating the coagulation and complement systems, thereby inducing systemic inflammatory response syndrome (SIRS)." (PMID 41169382, 2025). "IL-1β, IL-6, and TNF-α are common proinflammatory factors and are the most influential factors in the development of posttraumatic systemic inflammatory response syndrome (SIRS)." (PMID 37038178, 2023). "Similar trends were observed with IL-1β and CXCL-1, suggesting a decreased likelihood of progression to a systemic inflammatory response syndrome-like state." (PMID 35465347, 2022).
systemic inflammatory response syndrome (continued). "Proinflammatory cytokines, including IL-1β, IL-6, and HMGB1, mediate the inflammatory response of immune cells and promote systemic inflammatory response syndrome." (PMID 34790828, 2021). "It has been described that cinnamaldehyde inhibits the IL-1β and TNF-α production of macrophages stimulated by LPS in vitro, as well as in systemic inflammatory response syndrome in vivo." (PMID 32759721, 2020). "Excessive systemic release of IL-1β, however, strongly contributes to the pathogenesis of life-threatening systemic inflammatory diseases including systemic inflammatory response syndrome (SIRS)." (PMID 29922281, 2018). "Serum molecules like IL-1β, IL-6, TNF-α, ICAM-1, and E-selectin were involved in the pathophysiology of systemic inflammatory response syndromes." (PMID 24693284, 2014). "Systemic inflammatory response syndrome is characterized by increased serum levels of TNF-α, ICAM-1, E-selectin, IL-1β, and IL-6." (PMID 24369441, 2013). "Furthermore, serum acetylcholine (ACh) reduces the production of inflammatory cytokines (TNF-α, IL-1β, IL-6, and IL-18) through the alpha 7 nicotinic acetylcholine receptor subunit (α7nAChR) hereby preventing systemic inflammatory response syndrome (SIRS) development." (PMID 40299464, 2025). "Interestingly, IL-1β, a final product of NLRP3 inflammasome activation, is observed to play a significant role in NET formation and induces NETosis in systemic inflammatory response syndrome (SIRS) and abdominal aortic aneurysms (AAA)." (PMID 36851139, 2023). "In the early stage of ALI, local neutrophils and macrophages infiltrate in the lung tissues and secrete various cytokines like TNF-α, IL-6, and IL-1β, which can further activate leukocytes and cause systemic inflammatory response syndrome (SIRS) if inflammation is not controlled." (PMID 35264058, 2022). "Specifically, we found of significant elevation of the inflammatory cytokines IL-1β, TNF-α, IL-6, and CXCL1 in the peripheral circulation at P10, around human term age equivalent, in POE rats suggesting a systemic inflammatory response syndrome (SIRS)-like response." (PMID 37396628, 2022). "For three decades, the production of proinflammatory cytokines, such as IL-1β, IL-6, IL-8, and TNF-α, by leukemic cells in ATRA-differentiated APL patients has been recognized to result in DS and subsequent systemic inflammatory response syndrome (SIRS)." (PMID 41184249, 2025). "The in vitro release of pro-inflammatory cytokines such as interleukin (IL)-1β, IL-6, IL-8, and tumor necrosis factor-α (TNF-α) have been reported to coincide with ATRA-induced differentiation of APL blasts, which may lead in vivo to a systemic inflammatory response syndrome (SIRS)." (PMID 32859169, 2020).